MIR4707 (microRNA 4707)
Synonyms: hsa-mir-4707; mir-4707
Gene: MicroRNA gene on chromosome 14 (22,956,950 to 22,957,029, reverse strand). Ensembl gene ENSG00000284118.
Homologues: Orthologues: chimpanzee MIR4707 (100% identical).